DAO (D-amino acid oxidase)
Diseases named in the same sentence as DAO in open-access papers (continued):
Sharing a sentence is not in itself a finding about the gene and the disease.
schizophrenia (continued). "SRR immunoreactivity was increased in schizophrenia, but unlike DAO, this occurred in the DPFC not the cerebellum, and was not accompanied by elevated SRR mRNA." (PMID 17880399, 2007). "DAO has been shown to reduce NMDAR-mediated neurotransmission and thus increased DAO in schizophrenia might contribute, via d-serine decrements, to NMDAR dysfunction." (PMID 17880399, 2007). "However, it is important to note that the rapid metabolism of D-serine by the enzyme D-amino acid oxidase (DAAO) may reduce its bioavailability, potentially posing a challenge for its therapeutic use in schizophrenia." (PMID 39408997, 2024). "In contrast to NMDAR antagonists, two recent randomized, double-blind, placebo-controlled trials demonstrated that adjunctive therapy with benzoate, a D-amino acid oxidase inhibitor, improved cognitive function and the negative symptoms of patients with schizophrenia." (PMID 33114753, 2020). "Furthermore, inhibition of D-amino acid oxidase (major degradation enzyme of D-serine in the central nervous system) improved cognitive function and the negative symptoms of patients with schizophrenia." (PMID 33114753, 2020). "Besides, the interaction between DAO and RASD2 has provided an insight in integrating the glutamate and dopamine hypotheses of schizophrenia." (PMID 23555897, 2013). "One possibility, given our demonstration of DAO and SRR in Bergmann glia and unchanged cerebellar SRR in schizophrenia, is that a putative increased DAO could impact Bergmann glia d-serine levels and thence, speculatively, their regulation of synaptic input to Purkinje neurons." (PMID 17880399, 2007). "Furthermore, Ono and colleagues reported a significant elevation in DAO expression in choroid plexus epithelial cells, hypothesizing a subsequent reduction in D-serine cerebrospinal levels in schizophrenia." (PMID 35883465, 2022). "Thus, there is an urgent need for new drugs for the treatment of negative symptoms and cognitive deficits of schizophrenia, which might be achieved by understanding the interaction between DAO and DAOA, and their subsequent effect on NMDA receptors." (PMID 29114206, 2017). "The association between the AAGC haplotype and poorer MMN implies that the haplotype AAGC might have negative impact upon DAO activity (maybe elevation), next lower the function of NMDA receptor, then influence MMN index, and at last elevate the risk of schizophrenia." (PMID 26986737, 2016). "Although the effects of these DAO and DAOA nucleotide variations on their mRNA and protein expression in schizophrenia is not yet studied, these genes still remain as candidate genes for schizophrenia because of their role in the glutamatergic signaling." (PMID 29114206, 2017). "The lack of significant methylation and expression changes in DAO, G72, SR and DDO genes between patients with schizophrenia and non-psychiatric controls could be due to several reasons." (PMID 29976992, 2018). "Our finding of increased DAO mRNA in the cerebellum, without any change in SRR expression, may offer support to this hypothesis, and extends a preliminary study that also found increased cerebellar DAO mRNA in schizophrenia." (PMID 17880399, 2007).
Cognitive impairment (16 papers, 2013 to 2025). Abnormal cognition is characterized by deficits in thinking, reasoning, or remembering. "This study aims to examine whether DAO was over-expressed in people with age-related cognitive deficits, and could serve as a surrogate diagnostic biomarker." (PMID 29093468, 2017). "Thus, a variation that attenuates the activity of either NRG1 or PTK2B (human orthologs of Nrg1 and Pyk2) is likely to enhance the cognitive deficits caused by DAO protein." (PMID 23555897, 2013). "The NMDAR ‘glycine modulation site’ is a direct or indirect common target for D-serine, D-cycloserine, glycine transport protein 1 inhibitors and D-amino acid oxidase inhibitors, which are promising agents for improving cognitive impairment in schizophrenia." (PMID 38086803, 2023). "In other words, the cognitive deficits are expected to be even more severe when the DISC1 and DAO polymorphisms co-existed in the same cell." (PMID 23555897, 2013). "Arsenic exposure model of offspring mice was established and intervened with 6-chlorobenzo[d]isoxazol-3-ol (CBIO), a D-amino acid oxidase (DAAO) inhibitor, to explore the role of DAAO in cognitive impairment of offspring mice induced by arsenic during early developmental stage." (PMID 41021578, 2025). "In the future, the potential relationship of DAO levels and amino acids levels with treatment response for AD or a subpopulation of AD) requires clarification from larger samples of patients with different severities of cognitive deficits and under various treatments." (PMID 29093468, 2017). "However, whether DAO and amino acids levels in patients with cognitive impairment really progress with aging needs further elucidation by prospective study." (PMID 29093468, 2017). "In addition, we did not consider cognitive impairment without dementia, the severity of any depression, or the concurrent medication with NMDA antagonists; these factors may limit our power to illuminate the role of DAO in the deteriorating cognitive process." (PMID 31105635, 2019).
amyotrophic lateral sclerosis (14 papers, 2013 to 2025). "Impaired enzymatic activity in D-amino acid oxidase (DAAO) caused by missense mutations has been shown to trigger amyotrophic lateral sclerosis (ALS) through an abnormal accumulation of D-serine in the spinal cord." (PMID 33051492, 2020). "Furthermore, a mutation in DAO was recently linked to a familiar form of amyotrophic lateral sclerosis (ALS), which is a fatal human disease with neurodegenerative aspects affecting predominantly motor neurons." (PMID 26686055, 2016). "We have investigated a pathogenic mutation in D-amino acid oxidase (DAO), DAOR199W, associated with familial Amyotrophic Lateral Sclerosis (ALS) that impairs D-serine metabolism and causes protein aggregation, autophagy and cell death in motor neuron cell lines." (PMID 29487852, 2018). "As an illustration, an aberrant relative abundance of alternatively spliced RNA isoforms of the SNCA, SRRM2, DAO, SHANK3, CACNA1C, and TSC2 genes has been observed in the brains of patients suffering from amyotrophic lateral sclerosis, autism spectrum disorder, and Parkinson’s disease." (PMID 39858933, 2025). "It has been reported that the splicing of the APP, APOE, SNCA, MAPT, DAO, SHANK3, and CACNA1C genes, which are recorded in the PsyGeNET database, were abnormal in patients with neurological diseases such as Parkinson’s disease, Alzheimer’s disease, and amyotrophic lateral sclerosis." (PMID 39858933, 2025).
Alzheimer disease (9 papers, 2014 to 2025). A progressive, neurodegenerative disease characterized by loss of function and death of nerve cells in several areas of the brain leading to loss of cognitive function such as memory and language. "Sodium benzoate (a D-amino acid oxidase [DAO] inhibitor) has been found to improve the cognitive function of patients with early-phase Alzheimer’s disease (mild Alzheimer’s disease or MCI)." (PMID 33406269, 2021). "A recent study demonstrated that sodium benzoate, a D-amino acid oxidase inhibitor, improved cognitive function in early-phase Alzheimer disease." (PMID 33881530, 2021).
dementia (8 papers, 2016 to 2022). Loss of intellectual abilities interfering with an individual's social and occupational functions. "Furthermore, plasma DAO levels have also increased in post-stroke dementia patients, suggesting an effective biomarker for the diagnosis of dementia." (PMID 35225861, 2022). "Multiple regression of D-amino acid oxidase (DAO, ng/ml) between post-stroke dementia (PSD), and post-stroke without dementia (PSNoD) patients." (PMID 31105635, 2019). "The DAO levels in patients using anti-dementia drugs were also very similar to those without anti-dementia drugs in the matched cohort." (PMID 29093468, 2017).
bipolar disorder (7 papers, 2009 to 2023). A disorder of the brain that causes unusual shifts in mood, energy, activity levels and the ability to carry out day-to-day tasks. "It has been recently proposed that decreased expression of d-amino acid oxidase (DAO) in cerebellar neurons might increase the risk for bipolar disorder by affecting the regulation of N-methyl-d-aspartate receptors (NMDARs)." (PMID 36752514, 2023). "Using the ARAX web browser interface, we explored the connection between DAO and bipolar disorder via protein intermediaries in the context of a two-hop query graph (e.g. ‘DAO—*-—bipolar disorder’ where * represents a peptide/protein mediator)." (PMID 36752514, 2023).
cognitive decline (7 papers, 2017 to 2023). "The results show promise for D-amino acid oxidase inhibition as a novel approach for perceived stress and cognitive decline among patients with late-life depression." (PMID 35023557, 2022). "Following the pilot study on sodium benzoate for the treatment of cognitive function of early-phase AD, the current study further supports that DAO could serve as a novel target of drug development for early stages of cognitive decline." (PMID 33406269, 2021). "Taken together, peripheral DAO levels are higher in patients with cognitive decline." (PMID 29093468, 2017).
glioblastoma (6 papers, 2017 to 2021). The most malignant astrocytic tumor (WHO grade IV). "Moreover, another study found that DAOA even decreases DAO activity in human glioblastoma U87 cell line." (PMID 29114206, 2017). "The combination of the choline binding domain of the amidase N-acetylmuramoyl-L-alanine (CLytA)-D-amino acid oxidase (DAAO) (CLytA-DAAO) and D-Alanine induces cell death in several pancreatic and colorectal carcinoma and glioblastoma cell lines." (PMID 33198289, 2020).
depression (5 papers, 2018 to 2025). "Isofraxidin has a good docking with DAO, suggesting that isofraxidin may alleviate depression symptoms by regulating DAO." (PMID 35990602, 2022). "This study aims to compare sodium benzoate (a D-amino acid oxidase inhibitor and an indirect N-methyl-D-aspartate receptor enhancer), sertraline (a selective serotonin reuptake inhibitor), and placebo in the treatment of late-life depression." (PMID 35023557, 2022).
Psychosis (4 papers, 2013 to 2022). "In a 3-year prospective study cohort of 185 individuals (age: 13–35 years) at high risk and ultra-high risk (UHR) for psychosis, we assessed DAO (rs3918347, rs4623951), DAOA (rs778293, rs3916971, rs746187), and NRG1 (rs10503929) SNPs and their mRNA expression." (PMID 29326614, 2017). "We were unable to detect DAO and DAOA mRNA using qRT-PCR in the whole blood of individuals at-risk for psychosis, which is in line with a study that used RNA sequencing to detect DAO and DAOA mRNA in healthy participants." (PMID 29326614, 2017). "We examined associations of DAO, DAOA, and NRG1 SNPs with risk profiles in individuals at risk for psychosis." (PMID 29326614, 2017). "Considering the evidence of D-serine-mediated NMDAR modulation and the relevant role in D-amino acid metabolism exerted by the oxidase, it is not surprising the growing interest in DAO as a possible neurobiological target for treating psychotic disorders." (PMID 35883465, 2022).
chronic kidney disease (3 papers, 2017 to 2022). Impairment of the renal function secondary to chronic kidney damage persisting for three or more months. "In this study, we demonstrated a negative correlation between plasma DAO levels and eGFR, which was further supported by the high DAO levels found in patients with chronic renal disease." (PMID 31105635, 2019). "Both markers were not elevated in our cohort of ESRD patients, in contrast to our previous findings, where we found elevated DAO, lipopolysaccharide binding protein and sCD14 levels in chronic kidney disease stage G3-5 patients, HD and PD patients and patients after kidney transplantation." (PMID 29142271, 2017). "In chronic renal failure rats, TFA administration improved renal injury, remodeled gut microbiota dysbiosis, including regulated intestinal-derived metabolites such as D-serine, D-amino acid oxidase, L-serine, and serine racemase, suppressed the levels of pro-inflammation (TNF-α and IL-1β)." (PMID 35123452, 2022).
Stroke (3 papers, 2019 to 2021). Sudden impairment of blood flow to a part of the brain due to occlusion or rupture of an artery to the brain. "Plasma DAO levels were higher in the stroke patients (291 ± 111 ng/ml) than in the NC (217 ± 84 ng/ml) (Mann-Whitney U-test, P < 0.0001)." (PMID 31105635, 2019). "High plasma DAO levels were found in the stroke patients with high WMH loads (r = 0.34, P = 0.0335)." (PMID 31105635, 2019). "Plasma DAO levels negatively correlated with eGFR in stroke patients (r = –0.47, P < 0.0001) and controls (r = –0.44, P = 0.0003)." (PMID 31105635, 2019). "Since ischemic injury induces peroxisome biogenesis in neurons, DAO expression may also be regulated after stroke." (PMID 31105635, 2019). "First, DAO catalyzes D-serine to toxic metabolites (i.e., imino-serine, hydrogen peroxide, and ammonia), leading to oxidative stress and interference with stroke recovery." (PMID 31105635, 2019). "Since DAO is expressed mainly in the peroxisomes, high peripheral DAO levels in chronic stroke patients may suggest that peroxisome biogenesis is activated in the chronic stage of stroke." (PMID 31105635, 2019). "We found that plasma DAO levels were independently higher in PSD subjects than in PSNoD subjects or the controls and were correlated with the WMH load in stroke patients." (PMID 31105635, 2019). "The difference in plasma DAO levels between PSNoD and PSD groups was not affected by age, gender, time post-stroke, renal function, or HTN, suggesting that DAO is an independent marker for PSD." (PMID 31105635, 2019).
acute kidney injury (2 papers, 2019 to 2025). Sudden and sustained deterioration of the kidney function characterized by decreased glomerular filtration rate, increased serum creatinine or oliguria. "d-serine administration prevents kidney damage in murine models of acute kidney injury, and risperidone inhibits the activity of d-amino acid oxidase, which regulate plasma d-amino acid levels." (PMID 41348726, 2025). "Unexpectedly, cisplatin-induced acute kidney injury did not significantly alter renal DAO activity (P = 0.1355), which suggested renal DAO activity was preserved even with relatively severe proximal tubular damage." (PMID 31723194, 2019).
Anxiety (2 papers, 2015 to 2016). Intense feelings of nervousness, tension, or panic often arise in response to interpersonal stresses. "It is now apparent that the inactivation or deletion of DAO can both heighten anxiety and improve memory performance in multiple domains, including both long‐term and short‐term memory tasks, of both a spatial and non‐spatial nature." (PMID 25816902, 2015). "Although this could reflect species differences, it will remain important to assess anxiety in future clinical studies; it is possible that heightened anxiety could result from chronic but not acute DAO inhibition." (PMID 25816902, 2015).
colitis (2 papers, 2025). Inflammation of the colon. "Notably, LTA can improve the intestinal permeability induced by heat stress or colitis by reducing DAO activity, D-LA levels, and serum LPS levels." (PMID 40005048, 2025).
gastric cancer (2 papers, 2019 to 2024). A primary or metastatic malignant neoplasm involving the stomach. "The DAO gene, responsible for encoding diamine oxidase, has been linked to allergic reactions, and intriguingly, mutations in this gene might contribute to the incidence of gastric cancer." (PMID 38297313, 2024). "Simultaneous treatment with a DAO inhibitor to block the production of H2S abrogated this protective effect of d-Cys, indicating that this DAO-dependent H2S-generating pathway could contribute to the development of gastric cancer." (PMID 31547425, 2019).
glioma (2 papers, 2010 to 2021). A benign or malignant brain and spinal cord tumor that arises from glial cells (astrocytes, oligodendrocytes, ependymal cells). "Moreover, the rat C6 glioma cells lack functional DAO despite expressing it." (PMID 20091774, 2010). "Here we report studies in C6 glioma cells, which “simulate” the forebrain, in that the cells express SRR and ASCT2 but lack DAO activity." (PMID 20091774, 2010). "We have measured SRR and DAO expression and activity, [3H]D-serine uptake, and ASCT2 mRNA expression in C6 glioma cells 48 hr after the addition of serine isomers." (PMID 20091774, 2010).
Hypertension (2 papers, 2019 to 2025). The presence of chronic increased pressure in the systemic arterial system. "In conclusion, our data support that plasma DAO levels were increased in PSD patients and correlated with brain WMH, independent of age, gender, hypertension, and renal function." (PMID 31105635, 2019).
idiopathic pulmonary fibrosis (2 papers, 2024 to 2025). Idiopathic pulmonary fibrosis (IPF) is a nonneoplastic pulmonary disease that is characterized by the formation of scar tissue within the lungs in the absence of any known cause. "In addition, Dao−/− mice were more susceptible to BLM-induced pulmonary fibrosis compared to Dao+/+ mice, confirming the correlation between DAO expression and the process of pulmonary fibrosis." (PMID 39323641, 2024). "Thus, DAO may play an important role in the process of pulmonary fibrosis and enhance the therapeutic effect of T3." (PMID 39323641, 2024). "We analyzed DAO gene expression in patients with IPF and mice with bleomycin (BLM)-induced lung fibrosis." (PMID 39323641, 2024).
mood disorder (2 papers, 2019 to 2022). A cognitive disorder a disturbance in which the person's mood is hypothesized to be the main underlying feature. "Another novel NMDAR enhancer which looks promising in the treatment of mood disorders is sodium benzoate, a D-amino acid oxidase (DAAO) inhibitor which prevents degradation of D-amino acid." (PMID 35492692, 2022).
aortic aneurysm (1 paper, 2025). A ruptured aneurysm located in the wall of the proximal portion of the descending aorta proceeding from the arch of the aorta. "We pursued a chemogenetic approach to create an animal model of aortic aneurysm formation using a transgenic mouse line, DAAO-TGTie2, that expresses yeast d-amino acid oxidase (DAAO) under control of the endothelial Tie2 promoter." (PMID 40100302, 2025).
attention deficit-hyperactivity disorder (1 paper, 2024). A disorder characterized by a marked pattern of inattention and/or hyperactivity-impulsivity that is inconsistent with developmental level and clearly interferes with functioning in at least two settings (e.g. at home and at school). "Administration of D-amino acid oxidase (DAAO, d-serine degrading enzyme) inhibitor rescued attention-deficit/hyperactivity disorder (AD/HD) symptoms." (PMID 38979499, 2024).
bone cancer (1 paper, 2019). A primary or metastatic malignant neoplasm affecting the bone or articular cartilage. "On another note, DAO has also been implicated in the induction of pain in bone cancer." (PMID 31547425, 2019).
cholera (1 paper, 2023). "DAO protects the mucosal surface of the small intestine from cholera pathogens and reflects the integrity of the intestinal mechanical barrier and the degree of damage sustained." (PMID 37042787, 2023).
cystinosis (1 paper, 2019). Cystinosis is a metabolic disease characterized by an accumulation of cystine inside the lysosomes, causing damage in different organs and tissues, particularly in the kidneys and eyes. "However, LEA rats carry various other mutations such as impaired glucose tolerance, X-ray hypersensitivity, and lack of d-amino acid oxidase activity, and are, therefore, not necessarily suitable as a cystinosis model." (PMID 30591971, 2019).